EPCAM (epithelial cell adhesion molecule)
Diseases named in the same sentence as EPCAM in open-access papers (continued):
Sharing a sentence is not in itself a finding about the gene and the disease.
breast carcinoma (continued). "Targeting EpCAM with different antibody formats has been performed in colorectal as well as breast cancers." (PMID 32849491, 2020). "Simultaneous treatment of breast carcinoma-bearing mice with anti-EpCAM fusion toxin based on LoPE and HER2-specific liposomes loaded with Barnase leads to concurrent elimination of primary tumor and metastases." (PMID 33081407, 2020). "In breast cancer, EpCAM expression was correlated with favorable prognosis in the HER2 molecular subtype, and with unfavorable prognosis in the basal-like and luminal molecular subtypes." (PMID 32764280, 2020). "After characterization and optimization of the microfluidic method, we employed our system to investigate the expression profiles of HER‐2, EpCAM, and G‐CSF of several breast cancer cell lines." (PMID 32537399, 2020). "They reported that ectopic expression of EpCAM in murine fibroblasts and mouse mammary carcinoma cells induced clustering and segregation of cells and reduced invasive growth." (PMID 32507912, 2020). "A clinical study has shown that coexpression of both HER2 and EpCAM at high levels correlates with poor prognosis in breast cancer patients, suggesting that a drug targeting both these moieties would be highly beneficial to these high-risk patients." (PMID 33081407, 2020). "DNA hypomethylation at the EpCAM promoter region has been frequently observed in several cancer types such as in colorectal, ovarian and breast cancer." (PMID 32046162, 2020). "In breast cancers, the expression of EpCAM is correlated to CSC-like phenotypes that promote formation of bone metastases in mice." (PMID 32849491, 2020). "First, we evaluated the ALDH activity, the expression of BCSC genes (Nanog, Sox2 and Oct4), multiresistance pumps (ABCG2, ABCC1 and ABCB1) and the BCSC frequency (CD44+CD24+CD49+EPCAM+) in three human breast cancer cell lines." (PMID 33184339, 2020). "EpCAM overexpression is frequently observed in cancer tissue samples from patients with colon, stomach, prostate, kidney, ovary, liver, lung, and breast cancer, and correlates with poorer prognosis." (PMID 32764280, 2020). "In a recent study, all three EpCAM’s N-glycosylated Asn residues were mutated to Gln, and ectopically expressed in MCF-7 and MDA-MB-231 breast cancer cells." (PMID 32046162, 2020). "EpCAM+ aneuploid rare cells in peripheral blood and BM significantly correlated with systemic metastasis in breast cancer patients." (PMID 32599893, 2020). "A recent study on breast cancer, for instance, has revealed that the EpCAM+ breast cancer cells have the propensity to self-renew and differentiate, and are more aggressive in-vivo as compared to their EpCAM-counterpart." (PMID 32046162, 2020). "SS-inducible genes such as the Egr1 drive expression of Ap1, a transcription factor composed of protein dimers of c-JUN and c-FOS, which contributes to EPCAM-dependent breast cancer invasion." (PMID 30651129, 2019). "EpCAM expression as determined by publicly available gene array data is significantly lower in Basal B human breast cancer cell lines, which exhibit enhanced mesenchymal-like features, than in the Luminal and Basal A subgroups." (PMID 31234417, 2019). "Taken together, these data suggest that EpCAM plays a critical role in the metastatic process of breast cancer." (PMID 31443698, 2019). "Similar results were observed in epithelial cell adhesion molecule (EpCam)-positive breast cancer cells with the EpCam-specific antibody C215." (PMID 30925921, 2019). "EpCAM is frequently overexpressed across a wide range of human cancer, including pancreatic adenocarcinoma, breast cancer, ovarian cancer, and head and neck squamous cell cancer." (PMID 31324239, 2019). "We have identified that EpCAM plays a role in the metastasis of breast cancer cells to the lymph node." (PMID 31443698, 2019). "EpCAM positive circulating breast cancer cells were enriched for TACSTD2 expression linking it to a higher metastatic capability of tumor cells." (PMID 31772156, 2019).
breast carcinoma (continued). "In a subsequent study, the same team showed that the transcription factor activator protein 1 (AP-1) is an important downstream mediator of EpCAM signaling in breast cancer biology through the MEKK1-MKK7-JNK cascade." (PMID 31225512, 2019). "Collective expression of breast cancer cell surface markers (EpCAM, EGFR, and HER2) using a cocktail of target-specific antibodies was assessed." (PMID 30871481, 2019). "Two upregulated (EpCAM, FADD) and two downregulated (NDRG1, αB-crystallin) proteins were associated with the progression of breast cancer." (PMID 31443698, 2019). "Other studies have reported that changes in plasma EV EpCAM levels correlate with ovarian cancer and breast cancer." (PMID 31921310, 2019). "Inoculation into immunocompetent mice of pure EpCAM+ or EpCAM- breast cancer cells, sorted by flow cytometry, led to the detection of mixed EpCAM+/EpCAM- cells in the blood stream after a couple of days." (PMID 31367241, 2019). "In this analysis, we found a gradual rise of ECPAM gene expression related to increasing tumor grades and prognostic index status, indicating an increase in EPCAM expression during breast cancer progression." (PMID 31225512, 2019). "The aim of the current study was to evaluate the prognostic significance of TWIST1, CD24, CD44, and ALDH1 mRNA quantification in EpCAM-positive circulating tumor cells from early stage breast cancer patients with a long follow-up." (PMID 31261917, 2019). "In conclusion, detection of TWIST1 overexpression and stem-cell (CD24, CD44, ALDH1) transcripts in the EpCAM+ CTC fraction provides prognostic information in early stage breast cancer patients." (PMID 31261917, 2019). "These heterotypic clusters were detected in melanoma (Melanoma CTCs: CD45−/CD34−/CD90−/CD105−/CD73− but CD146+/MelA+ cells), as well as in breast cancer patients’ blood (Breast cancer CTCs: EpCAM+/PanCK+/DAPI+ but CD45− cells)." (PMID 31003475, 2019). "They used this platform to discriminate the EpCAM(+) EVs level in serum between 2 breast cancer patients and 5 healthy individuals." (PMID 31212643, 2019). "The dynamic EMT and MET was also observed in parental and HCC38 cells delineated by EpCAM profiling, in Zeb1 driving CD44Low to CD44High cellular plasticity and in mammary carcinoma mouse MyPT models delineated by E-cadherin profiling." (PMID 31234417, 2019). "To re-evaluate clinical relevance of EPCAM gene expression we utilized in a large published breast cancer cohort by using the Breast Cancer Gene-Expression Miner v4.1." (PMID 31225512, 2019). "In this study we evaluated for the first time the prognostic significance of TWIST1, CD24, CD44, and ALDH1 transcript quantification in EpCAM-positive circulating tumor cells isolated from peripheral blood of early stage breast cancer patients." (PMID 31261917, 2019). "In 2004, the U.S. Food and Drug Administration (FDA) approved an epithelial cell adhesion molecule (EpCAM)-dependent technique for use as a prognostic biomarker in breast cancer, which was then expanded for use in prostate and colorectal cancer patients." (PMID 31053984, 2019). "Similar observations were made in a PMC42-LA breast cancer cell line where EpCAM levels were used to segregate cells as epithelial (EpCAM+) or mesenchymal (EpCAM−)." (PMID 31557977, 2019). "They demonstrated a significantly higher level of EpCAM(+) EVs in breast cancer patient plasma than in healthy controls." (PMID 31212643, 2019). "We have delineated epithelial and mesenchymal subpopulations existing within the PMC42-LA breast cancer cell line by their EpCAM expression." (PMID 31234417, 2019). "In breast cancer, EpCAM was down-regulated in mesenchymal lines relative to the epithelial cell lines and in EMT-induced breast cancer cells." (PMID 31225512, 2019). "EpCAM siRNA treatment resulted in a significant decrease in cell proliferation in breast cancer cell lines." (PMID 31225512, 2019).
breast carcinoma (continued). "The main limitation of our study is that we examined the expression of only one EMT marker, TWIST1 in the EpCAM+ cells of early breast cancer patients." (PMID 31261917, 2019). "By using a microfluidic chip to quantify exosomes, circulating EpCAM-positive exosomes were detected in six breast cancer patients and three healthy controls and were found to be comparative with healthy controls." (PMID 31514467, 2019). "EpCAM is expressed in many types of human cancer, such as breast cancer, gastric cancer, and colorectal cancer." (PMID 31324239, 2019). "Detection and serial monitoring of cells expressing the epithelial surface molecule EpCAM in peripheral blood of patients with hormone receptor positive breast cancer was used to follow the fate of these cells during endocrine e treatment." (PMID 30380648, 2018). "We isolated small pools of (~20) EPCAM-positive DTCs from early breast cancer patients for genomic profiling." (PMID 30211312, 2018). "Nevertheless in established cell lines, MDA-MB-231 and BT-20, EPHB6 presence did not expand CD24loCD44hi or ALDH1-positive subpopulations, selectively increasing EpCAM expresion that represents some breast cancer TICs." (PMID 29700392, 2018). "In this study, we applied IE/FACS to detect and isolate pools of EPCAM-expressing DTCs from bone marrow of early breast cancer patients." (PMID 30211312, 2018). "Intriguingly, a recent study found a subset of ALDH+/CD49f+/EpCAM+ cells in normal tissue adjacent to a breast cancer expressed a hybrid basal/luminal phenotype." (PMID 29606612, 2018). "In this report, the cells of interest are a model for CTCs, MCF-7 breast cancer cells and lung tumour cells from a subcutaneous non-small cell lung cancer model that both express EpCAM." (PMID 29895867, 2018). "Knockdown of TET2 in breast cancer cells decreases epithelial cell adhesion molecule and E-cadherin, increasing cell invasiveness." (PMID 30062102, 2018). "The epithelial cell adhesion molecule (EpCAM) is another molecule that is upregulated in prostate cancers, as well as in breast cancers, where it is expressed 100–1000-fold greater than normal cells." (PMID 29751641, 2018). "The samples for these holograms were prepared by labeling SkBr3 breast carcinoma cells with polystyrene beads conjugated with control, EpCAM, and HER2 antibodies." (PMID 30451953, 2018). "As expected, the mixture of breast cancer cells and splenocytes are clearly distinguished and sorted using EpCAM and CD45 antibodies." (PMID 30389926, 2018). "EpCAM expression was retained and further evaluation of the BRx142 cell line by qPCR confirmed that common breast cancer biomarkers tested were unaltered by vitrification." (PMID 29474365, 2018). "EpCAM is one of the cell surface markers used for the identification of CSCs from various epithelial cancers, including breast cancer." (PMID 30428522, 2018). "We demonstrate the feasibility of direct isolation and characterization of EPCAM-positive DTCs from early breast cancer patients." (PMID 30211312, 2018). "Inhibition of EGF-mediated ERK activation by full-length EpCAM has been reported in carcinoma cells, including breast cancer lines." (PMID 30261040, 2018). "We used EpCAM and CD49f that have been previously utilized to separate both normal human mammary epithelial cell and also breast cancer cells into different populations." (PMID 29162812, 2017). "The EPCAM-positive breast-cancer cells and colon-cancer cells expressed EPCAM on all 96 h, whereas they only expressed KRT19 and CDH2 from 0 to 72 h." (PMID 28975085, 2017). "MICs defined in breast cancer patients expressed EpCAM strongly, so that EpCAM-positive CTCs constitute therapeutic targets." (PMID 27683128, 2017). "It is also worth mentioning that the blood specimen of one early breast cancer patient that relapsed very early was found methylated in the EpCAM-positive CTC-fraction, for all genes tested, while it was CK-19 negative." (PMID 29069768, 2017).
breast carcinoma (continued). "The targeting capability of anti-EpCAM was further confirmed using the low EpCAM-expressing breast cancer cell line MDA-MB-231." (PMID 29872709, 2017). "Overexpression of EpCAM was detected in 35.6% breast cancer samples by the immunohistochemical method and was related to poor prognosis." (PMID 28931402, 2017). "It was shown that the level of plasma epithelial cell adhesion molecule (EpCAM)-positive exosomes was significantly higher in breast cancer patients compared with healthy individuals." (PMID 29282096, 2017). "Specifically, we showed that 4T1 TNBC cells have on average a 100-fold higher EpCAM expression than MDA-MB-231 breast cancer cells." (PMID 29872709, 2017). "The primary outcome will be the expression pattern of circulating CSC markers in breast carcinomas including EPCAM, CD44, CD24, ALDH1, CD133, and PIWIL2." (PMID 29258583, 2017). "They used an RNA aptamer specific for epithelial cell adhesion molecule (EpCAM) and a Dicer substrate survivin siRNA for the treatment of Dox-resistant breast cancer in vivo." (PMID 29132385, 2017). "The nucleus and the epithelial cell adhesion molecule (EpCAM)—a surface marker used to differentiate and classify breast cancer cells—were stained." (PMID 29257118, 2017). "EpCAM is expressed on certain carcinomas including ovarian cancer, breast cancer, lung cancer, pancreas cancer, colorectal cancer, head and neck squamous-cell carcinoma (HNSCC), and gastric cancer." (PMID 28931402, 2017). "Two cell lines, MDA-MB-231 and Michigan Cancer Foundation-7 (MCF-7), were selected as breast cancer cells, with two kinds of membrane protein, epithelial cell adhesion molecule (EpCAM) and epidermal growth factor receptor (EGFR), observed in both cells." (PMID 29257118, 2017). "Using the ISET platform and an epithelial-marker independent immunocytochemical assay we detected higher number of putative CTCs in early breast cancer samples than CTCs detected by the EpCAM/cytokeratin dependent CellSearch." (PMID 28422972, 2017). "Human breast cancer cells with CD44+/CD24−/EpCAM+ expression markers and/or possessing ALDH1 enzyme activity are recognized as CSCs and are responsible for maintaining tumor growth." (PMID 29069872, 2017). "A study demonstrated that high expression of EpCAM was a poor prognostic indicator of breast cancer with node-positive." (PMID 28931402, 2017). "Under the leadership of Wei Dun and Sarah Shigdar, a chemo-sensitizing approach using a Dicer substrate siRNA against survivin appended to an 18mer anti-EpCAM RNA-aptamer in a breast cancer xenograft mouse model was presented." (PMID 28792479, 2017). "The use of EpCAM as a marker for detecting disseminated breast cancer cells in bone marrow strongly suggests that EpCAM+ breast cancer cells possess an enhanced ability to metastasize." (PMID 28870198, 2017). "Circulating EpCAM-positive exosomes were measured in 6 cases breast cancer patients and 3 healthy controls to assist diagnosis." (PMID 28369094, 2017). "The enrichment and detection of CTCs in Cellsearch system is cell surface marker (EpCAM)-dependent; however, the expression of EpCAM in breast cancer cells is heterogeneous and dynamic." (PMID 28187533, 2017). "Blood samples from healthy individuals spiked with breast-cancer cells or colon-cancer cells were tested for expression of EPCAM and cMET." (PMID 28975085, 2017). "In early breast cancer, SOX17 promoter methylation in the EpCAM-positive CTC-fraction was associated with CK-19 mRNA expression (P = 0.006) and worse overall survival (OS) (P = 0.044)." (PMID 29069768, 2017). "The enumeration of EpCAM-positive circulating tumor cells (CTCs) has allowed estimation of overall metastatic burden in breast cancer patients." (PMID 28775303, 2017). "The detection rate of the breast cancer cell line SkBr3 was higher in both methods (mean IsoFlux: 49%, mean filtration: 80%) owing to the very high EpCAM expression and the large cell size compared to the pancreatic cancer cell lines." (PMID 29156783, 2017).
breast carcinoma (continued). "The AdnaTest Breast Cancer assay identified 15 of 34 CTC positive patients (44%) at BL (PCR based detection of EpCAM, HER2 or MUC1 transcript ≥ 15ng/ul)." (PMID 28489591, 2017). "It was demonstrated that the amount of EpCAM-positive exosomes showed significantly higher in the plasma of breast cancer patients than that in healthy controls." (PMID 28369094, 2017). "Our recent study showed decrease in CD24 and EpCAM expression in mammary cancer cells in rats after oregano treatment." (PMID 28524540, 2017). "E-cadherin, EMA, Her2/neu, CEA, and uPAR staining was positive in both the plasma membrane and cytoplasm of the breast cancer cells, whereas αvβ6 integrin, EpCAM, and FR-α staining was confined to the membrane." (PMID 26946151, 2016). "But overexpression of EGFR and HER2/Neu in primary breast cancer is reported to be 0.8-14 and 15-20% respectively, whereas 40-98% of the primary breast tumours show enhanced EpCAM levels." (PMID 27842504, 2016). "Enumeration of CTCs following epithelial cell adhesion molecule (EpCAM) based capture serves as a prognostic and predictive biomarker in different malignancies such as prostate and breast cancer, as well as non-small cell lung cancer (NSCLC)." (PMID 27459545, 2016). "One of the earliest papers looking at EMT in CTCs/DTCs observed an EMT-like gene expression signature in breast cancer cells purified from pleural effusions using anti-epithelial cell adhesion molecule (EpCAM) antibody MOC-31-conjugated immuno-magnetic beads." (PMID 27189371, 2016). "Further, anti EpCAM aptamer-mediated survivin silencing has been explored to sensitize breast cancer stem cells to Doxorubicin." (PMID 27827876, 2016). "Relative to the normal breast tissue, the CD49fHigh/EpCAM+ sub-population is enriched in tumors and is believed to mark the lineage that is the origin of luminal breast cancers." (PMID 27001172, 2016). "Four clinically relevant orthotopic tumour models, i.e. colorectal cancer, breast cancer, head and neck cancer, and peritonitis carcinomatosa, were used to evaluate the performance of the anti-EpCAM agent with the clinically validated Artemis imaging system." (PMID 27842504, 2016). "Using this model system, we analyzed the physical and molecular characters of EMT-induced breast cancer cells, which have low levels of EpCAM expression." (PMID 27013581, 2016). "Consistent with patterns of expression, Claudin low and Basal type breast cancer cell lines demonstrated the least recovery with EpCAM alone." (PMID 27049831, 2016). "As pointed out earlier, in copies per cell EpCAM can probably not compete with Her2/Neu in the subpopulation of Her2 positive breast cancers, but in percentage of positive breast tumours EpCAM is clearly the more prevalent target." (PMID 27842504, 2016). "For MCF-7 breast cancer cells similar EpCAM over-expression was observed as for HT29, whereas considerably less expression was seen in MDA-MB-231 cells." (PMID 27842504, 2016). "In order to understand the connection between EpCAM and breast cancer cell invasion/migration in more detail, it will be of great interest to identify signaling cascades by which EpCAM regulates these activities." (PMID 26356670, 2015). "Recently, a growing body of literatures suggests that over-expressed EpCAM facilitates tumor invasion and migration in breast cancer, colorectal cancer and thyroid cancers." (PMID 26698569, 2015). "Our results showed that EpCAM regulates breast cancer cell migration and invasion properties in cell culture." (PMID 26356670, 2015). "Trop2 gained notice because it was expressed in all breast cancer cell lines examined, in contrast to EpCAM (= Trop1) expression." (PMID 26695635, 2015). "To date, EpCAM overexpression has been indicated to be able to predict poor prognosis of the patients with renal cancer, breast cancer, prostate cancer, ovarian cancer and hypopharyngeal cancer, while its prognostic value was controversial in lung cancer." (PMID 26698569, 2015).